BRCA1 (BRCA1 DNA repair associated)
Diseases named in the same sentence as BRCA1 in open-access papers (continued):
Sharing a sentence is not in itself a finding about the gene and the disease.
triple-negative breast carcinoma (continued). "Over the 3-year period, only 1 VUS in BRCA1 was re-classified to benign in a patient with triple negative breast cancer." (PMID 35190596, 2022). "Defects in BRCA1, a gene involved in homologous recombination DNA repair, are common in triple negative breast cancer." (PMID 35304461, 2022). "This PV yield is similar to the 61 (48.8%) BRCA1/2 PVs identified in 125 women with triple-negative breast cancer." (PMID 33758026, 2022). "Those researchers found insignificant differences in survival, but triple-negative breast cancer patients harboring BRCA1/2m had a slight survival advantage in the first several years following their primary diagnosis." (PMID 35909902, 2022). "We have demonstrated that three different PARPis are known to target the PARP1/2 activity, olaparib, talazoparib, and veliparib, impair the VM formation of triple negative breast cancer cells, independently of the BRCA1/2 status." (PMID 36555812, 2022). "Out of the genes that have a role in the BRCA1/2 HR pathway, NCCN Guidelines (version 2.2021) indicate that the risk of triple negative breast cancer is potentially increased in patients with P/LP variants in BRIP1, RAD51C and RAD51D." (PMID 35710434, 2022). "The same group reported that knockdown of UBC9 in BRCA1 mutant triple-negative breast cancer and HGSOC cells inhibited cell proliferation and migration, indicating the pivotal role of UBC9 in endothelial-mesenchymal transition in such cancer type." (PMID 36193060, 2022). "With the development of poly (ADP-ribose) polymerase (PARP) inhibitors, the exact relationship between BRCA1/2 genes and sporadic triple negative breast cancer/high grade serous carcinoma (TNBC/HGSC) needs to be further investigated." (PMID 35986351, 2022). "Knocking down SPAG5 increased the S-phase cell population and decreased the expression of c-MYC target genes, including the DNA repair proteins RAD51 and BRCA1/2 in triple-negative breast cancer." (PMID 36304306, 2022). "The combination of NUSAP1 and BRCA1 improves the prognostic power in triple-negative breast cancer compared with the calculation based on age, menstrual status, and lymph node status." (PMID 35739489, 2022). "About 25% of all triple-negative breast cancers (TNBCs) and 10% to 20% of high-grade serous ovarian cancers (HGSOCs) harbor BRCA1 promoter methylation." (PMID 36074460, 2022). "Here, we show that the knockout of BRCA1 in triple-negative breast cancer (TNBC) cell lines increases their sensitivity to the OGG1 inhibitor TH5487, reflecting a possible synthetic lethal relationship between the two genes." (PMID 35619904, 2022). "As most patients with triple-negative breast cancer (TNBC) (60–80%) exhibit mutations in BRCA1 and AR activity is directly influenced by BRCA1, AR can potentially be a prognostic marker for TNBC14." (PMID 36450882, 2022). "Is mosaic BRCA1 promoter methylation in normal tissue associated with the risk of incident high-grade serous ovarian cancer (HGSOC) and triple-negative breast cancer (TNBC)?" (PMID 36074460, 2022). "Most studies found that germline BRCA1/2 carriers were at a higher risk of death than their BRCA-negative counterpart, but there are indications that triple-negative breast cancer patients who are BRCA1/2 carriers have a better prognosis." (PMID 34857041, 2021). "Expressing low levels of BRCA1 co-express either nuclear Snail or Slug was found in the majority of triple-negative breast cancer (TNBC) patients." (PMID 33589588, 2021). "In view of the much higher percentage of HRD tumors among triple negative breast cancer, the BRCA1-likeCGH classifier was further investigated in this group." (PMID 33670893, 2021).
triple-negative breast carcinoma (continued). "The prevalence of a germline BRCA1/2 mutation was reported to be 11.2% in unselected TNBC patients, which is significantly higher than its prevalence in non-triple-negative breast cancers, and the BRCA1 mutation was more common than BRCA245,46." (PMID 34448553, 2021). "BRCA1 driven triple negative breast cancer (TNBC) has been shown to arise from luminal progenitors yet little is known about how BRCA1 loss-of-function (LOF) and concomitant mutations affect the luminal progenitor cell state." (PMID 33686070, 2021). "BRCA1 promoter methylation has been reported in 30–35% of all triple-negative breast cancers with germline BRCA1/2 wild-type status, mainly the basal-like subtype." (PMID 32806509, 2020). "This study is to investigate the effect of the PI3K/Akt signaling pathway on the regulation of BRCA1 subcellular localization in triple-negative breast cancer (TNBC) MDA-MB-231 cells and hormone-sensitive T47D cells." (PMID 33817238, 2020). "RAD521–209 was stably expressed in BRCA1−/− triple-negative breast cancer cells, MDA-MB-436 and HCC1937, using lentiviral system." (PMID 33275133, 2020). "In triple-negative breast cancers treated with NAC, several studies have tried to identify the relationships between germline BRCA1/2 mutations, response rates, and prognoses." (PMID 32131779, 2020). "Within the treatment options for advanced triple negative breast cancer, the PARP inhibitor olaparib is only given to patients with BRCA1/2 mutations." (PMID 32630796, 2020). "Genistein can confer sensitivity to triple-negative breast cancer for antiestrogen therapy by preventing and reversing AhR-dependent BRCA1 hypermethylation." (PMID 32085612, 2020). "Methylation of the BRCA1 promoter is frequent in triple-negative breast cancers (TNBC) and leads to a tumor phenotype similar to BRCA1-mutated tumors." (PMID 33282730, 2020). "The decreased BRCA1 expression and the subcellular localization abnormalities have been observed in triple-negative breast cancer (TNBC)." (PMID 33817238, 2020). "We used PDX models from triple-negative breast cancer (TNBC) with neoadjuvant chemotherapy and/or germline BRCA1 mutations in chemosensitivity tests." (PMID 31821346, 2019). "Recently, a solid lipid nanoparticle formulation of Talazoparib was reported and has been tested in BRCA1 mutant triple negative breast cancer cell lines in vitro." (PMID 31534547, 2019). "Mutated in 20% of human cancers; doxorubicin resistant triple-negative breast cancer is associated with loss of SMARCB1, SMARCA4, or KEAP1 (a BRCA1 interactor)." (PMID 31287417, 2019). "We have provided an overview of the main clinical characteristics in correlation with 9–12 del BRCA1, highlighting the diagnosis of triple-negative breast cancer and high-grade papillary ovarian cancer." (PMID 31545835, 2019). "In this way, the correlation of carriers of 9–12 del BRCA1 with triple negative breast cancer was found, as well as high-grade papillary serous ovarian cancer." (PMID 31545835, 2019). "In taxane-resistant triple-negative breast cancer PDX tumors, CX-5461 reduced tumor growth and showed selective lethality in BRCA1/2-deficient tumors." (PMID 31817270, 2019). "More recently, defects in the homologous recombination system, such as BRCA1 and BRCA2 mutations have been associated with higher rates of response to platinum-based and anthracyclines regimens both in triple negative breast cancers (TNBCs) and EOCs." (PMID 30760286, 2019). "Taken together, our results provided evidence that there exists a reciprocal regulation between BRCA1 and β‐hCG in inducing tumorigenesis in BRCA1 defective triple negative breast cancer." (PMID 29460395, 2018). "Differences in tumour characteristics between BRCA1 and BRCA2 mutation carriers were also noted in patients with triple-negative breast cancer." (PMID 29337092, 2018).
triple-negative breast carcinoma (continued). "PI3K inhibition led to decreased BRCA1/2 expression and induced homologous recombination deficiency, which sensitized BRCA-proficient triple negative breast cancer to PARP inhibition." (PMID 29686231, 2018). "The authors also showed that adding the poly-ADP-ribose polymerase (PARP) inhibitor olaparib to PI3K inhibitors markedly attenuated tumor activity in triple negative breast cancer with wild-type BRCA1." (PMID 29942710, 2018). "In ER negative breast cancer, the MGMT promoter is frequently methylated in a BRCA1 dependent manner, with highest rate of MGMT promoter methylation (>60%) in wild-type BRCA1 triple negative breast cancer." (PMID 30038716, 2018). "Several cancers like triple negative breast cancers and ovarian cancers with wild type BRCA1 also exhibit sensitivity to PARP inhibitors." (PMID 28412751, 2017). "In contrast, of 425 screens in women with triple negative breast cancer, 151 (35.5%) resulted in positive BRCA tests with 117 (27.5%) having BRCA1 mutations and 34 (8.0%) BRCA2 mutations." (PMID 27796713, 2017). "In contrast to our RCC example, triple-negative breast cancer is generally characterized by a downregulated BRCA1 expression and an upregulated miR-146a expression." (PMID 26859141, 2016). "This biology is found in a subset of BRCA1-mutant and triple negative breast cancer cases and confers good outcome." (PMID 26943587, 2016). "In addition to BRCA1/2 mutations, perhaps as many as 35 % of patients with HSOC and triple-negative breast cancer may have other HR pathway defects, such as methylation-induced silencing of BRCA1/2, mutations in other DNA repair genes, or activation of HR inhibitors." (PMID 27613518, 2016). "In agreement, although both HCC70 and MCF-7 express wild-type BRCA1 and MDA-MB-468 has mutated BRCA1, MCF-7 is a luminal, while HCC70 and MDA-MB-468 are triple-negative breast cancer cell lines, which are more similar phenotypically to BRCA1-negative cells." (PMID 27043660, 2016). "We carried out a systematic analysis of 37 genetic variants in genes from the BRCA1 associated A complex including ABRAXAS, BRCC36, RAP80 BRE and NBA1, in a Chinese Han Women cohort, including 414 triple-negative breast cancer (TNBC) cases and 354 controls." (PMID 26848770, 2016). "We investigated the effects of miR-342 transfection in the triple-negative breast cancer cell lines MDA-MB-231 and HCC1937, the latter carrying a germ-line BRCA1 mutation." (PMID 26919240, 2016). "Our work provides evidence for the involvement of specific miRNAs in triple-negative breast cancer development through regulating BRCA1 expression." (PMID 26392359, 2015). "Here, we explored the expression of putative BRCA1-regulating miRNAs in sporadic human triple-negative breast cancer cells." (PMID 26392359, 2015). "Another potential biomarker of triple-negative breast cancer that we identified is miR-26a, and we found that miR-26a can down-regulate the expression of BRCA1 in MDA-MB-231 and MCF7 cells." (PMID 26392359, 2015). "BRCA1 promoter methylation was frequently found in triple negative breast cancers and identified a significant fraction of patients with poor outcomes." (PMID 25986046, 2015). "Methylation of the BRCA1 promoter is frequent in triple negative breast cancers (TNBC) and results in a tumor phenotype similar to BRCA1-mutated tumors." (PMID 25177489, 2014). "Our findings are in agreement with other studies; indeed, miR-146a has been described to target the 3′UTR of BRCA1 gene that is altered in almost triple negative breast cancer cases (25%)." (PMID 25369070, 2014). "Of clinical significance, treatment of human triple negative breast cancer cell lines with vorinostat was able to induce BRCA1 degradation and a subsequent BRCAness phenotype, which synergistically induced cell death in combination with PARPi or cisplatin." (PMID 24624361, 2014).
triple-negative breast carcinoma (continued). "To address this concern, we have explored the cellular responses of BRCA1-defective and triple-negative breast cancer cells, and in vitro BRCA1 interactions induced by the ruthenium(II) complexes containing the bidentate ligand, 5-chloro-2-(phenylazo)pyridine." (PMID 24507701, 2014). "Functionally, a recent study in triple negative breast cancer demonstrated that PI3K signaling was required for BRCA1 function." (PMID 24624361, 2014). "In the present study, CDDO-Im (100–200 nM) significantly induced apoptosis in SUM159 and MDA-MB-231 cells which are triple-negative breast cancer cells with wild-type BRCA1." (PMID 25229616, 2014). "Alteration in the function of the BRCA1 gene product has also been identified as an alternative route which also results in impaired BRCA1 function in triple-negative breast cancer." (PMID 23405268, 2013). "Our results indicated that BRCA1 promoter methylation correlated significantly with triple-negative breast cancer." (PMID 23405268, 2013). "Although, early onset of disease is usable as selection criteria for BRCA1 genetic testing among triple-negative breast cancer patients, age alone cannot predict BRCA1 involvement." (PMID 23704984, 2013). "We found reactivation of small modules of embryonic mammary epithelial genes within mouse Brca1-/- tumors and human basal-like/triple-negative breast cancers." (PMID 23506684, 2013). "In the present study, we scanned the whole coding regions of BRCA1, BRCA2, PALB2 and BRD7 in order to investigate the relative contributions of germ-line mutations in these genes to triple-negative breast cancer in a hospital-based series of German patients." (PMID 23110154, 2012). "In fact, we have recently initiated a Phase II clinical trial for gemcitabine, carboplatin and PARP inhibitor iniparib (BSI-201) in the neoadjuvant treatment of BRCA1 or BRCA2 mutated and triple-negative breast cancer." (PMID 21771338, 2011). "Homologous recombination defects are commonly seen in triple-negative breast cancer and include BRCA1 methylation, overexpression of de-regulators including ID4 and HMG as well as aberrations of MRE11, ATM and PALB2." (PMID 21989215, 2011). "Based upon these results, clinical trials have been initiated to examine the role of platinum drugs with gemcitabine in BRCA1- mutant and triple-negative breast cancers." (PMID 21771338, 2011). "Five deleterious BRCA1 mutations and one deleterious BRCA2 mutation were identified in the 54 patients with early-onset, triple-negative breast cancer (11%)." (PMID 19298662, 2009). "Frequently increased EGFR copy number and EGFR protein expression, and decreased BRCA1 mRNA expression, were observed in Japanese triple-negative breast cancers." (PMID 18950515, 2008). "BRCA1 mutations are most commonly associated with triple-negative breast cancer (TNBC), a subtype lacking the expression of estrogen receptor (ER), progesterone receptor (PR), and human epidermal growth factor receptor 2 (HER2)." (PMID 39997609, 2025). "A recent study evaluated BRCA1 promoter methylation by quantitative methylation-specific PCR and demonstrated that triple-negative breast cancer (TNBC) patients with a BRCA1 or BRCA2 mutation, or high BRCA1 promoter methylation, showed better 6-month PFS compared with the other patients (p = 0.009)." (PMID 40075848, 2025). "No mutation was found in BRCA1/2 gene test; immunohistochemical of surgical specimens showed triple negative breast cancer." (PMID 39138583, 2024). "The results indicate better overall survival in young triple-negative patients with pathogenic germline variants in BRCA1 or BRCA2 compared to triple-negative breast cancer without pathogenic variants, but not for other clinical subtypes." (PMID 38398129, 2024).
triple-negative breast carcinoma (continued). "Additionally, while these compounds reduce BRCA1 protein level in vitro in a triple-negative breast cancer cell model, further studies are necessary to evaluate the tissue-specificity of these compounds." (PMID 38993666, 2024). "Patients with triple-negative breast cancer without BRCA1 or BRCA2 mutations can benefit from immune checkpoint inhibitors." (PMID 38506114, 2024). "For Korean patients, a fivefold increase in CBC risk was observed for 132 triple negative breast cancer patients with BRCA1/2 germline mutation when compared to 868 BRCA1/2 negative patients." (PMID 38254240, 2024). "The triple negative breast cancer family has obvious familial heritability, but no potential pathogenic variation was found in BRCA1/2." (PMID 39138583, 2024). "Furthermore, other studies observed the highest prevalence of BRCA1 mutant tumors in triple-negative breast cancer patients similar to our findings." (PMID 37719058, 2023). "A phase Ib/2 clinical trial that combined BET inhibitor ZEN-3694 and talazoparib showed a response rate of 22% in patients with triple-negative breast cancer without germline BRCA1/2 mutations." (PMID 38069409, 2023). "Triple-negative breast cancer (TNBC), accounting for 10–15% of all breast malignancies, is more prevalent in women under 40, particularly in those of African descent or carrying the BRCA1 mutation." (PMID 37824496, 2023). "Our data suggest that about 20% of all triple-negative breast cancers may arise from BRCA1-methylated subclones of normal cells." (PMID 38053165, 2023). "Furthermore, we found that overexpression of TRIM47 resulted in reduced expression and half-life of BRCA1 but inhibited TRIM47 expression induced expression and half-life of BRCA1 in triple-negative breast cancer cells." (PMID 36906594, 2023). "Interestingly, this patient developed triple negative breast cancer (TNBC) at a young age, which is typically observed in BRCA1 mutation carriers." (PMID 37620397, 2023). "Analysis revealed a trend of favorable overall survival for patients with BRCA1/2 deleterious mutations, especially for triple negative breast cancer patients, although this trend was not statistically significant." (PMID 35494038, 2022). "In the US and the EU4, patients who were not tested versus tested for BRCA1/2mut were more likely to have hormone receptor–positive (HR+)/HER2− ABC than triple-negative breast cancer, less likely to have a known family history of BRCA1/2-related cancer and were older." (PMID 36358816, 2022). "Similarly, the TQ-induced apoptosis in triple-negative breast cancer cells was correlated with an increased expression of two TSGs, BRCA1 and HIC1, which also show well-documented repression in various tumors through hypermethylation of their promoters." (PMID 33922029, 2021). "A stop gained mutation in BRCA1 p.Arg1443Ter, dbSNP ID is rs41293455, population allele frequency is 0.00 in South Asia, identified in the youngest patient aged 31 diagnosed with triple negative breast cancer without any family history of cancer." (PMID 33773534, 2021). "Here, no germline BRCA1/2 mutations were detected in patients with triple-negative breast cancer, contrary to expectations." (PMID 33420229, 2021). "BRCA1-driven triple-negative breast cancer (TNBC), for example, has been shown to arise from luminal progenitor cells yet little is known about how BRCA1 loss-of-function (LOF) and concomitant mutations affect the luminal progenitor cell state and ultimately lead to transformation." (PMID 33686070, 2021). "Since some triple-negative breast cancers share the high-grade genomic instability observed in BRCA1/2-mutant cancers, the so-called BRCAness, we were interested in whether ROR2 could be linked to these changes." (PMID 34911552, 2021). "BRCA1 carriers have earlier-onset disease, particularly under age 50 and are more likely to develop aggressive triple-negative breast cancer than BRCA2 carriers or those who are BRCA mutation negative." (PMID 34228231, 2021).